BRCA1 (BRCA1 DNA repair associated)
Diseases named in the same sentence as BRCA1 in open-access papers (continued):
Sharing a sentence is not in itself a finding about the gene and the disease.
ovarian carcinoma (continued). "Epigenetic silencing of BRCA1 or RAD51C is a mechanism of homologous recombination deficiency in up to 5–30% of breast and ovarian cancers, with silencing of all BRCA copies (homozygous methylation) associated with improved PFS in response to rucaparib compared to BRCA1/2-intact cases." (PMID 37430137, 2023). "Women with pathogenic BRCA1 or BRCA2 variants are at high risk for breast and ovarian cancer." (PMID 37845719, 2023). "For example, BRCA1 and BRCA2 genes have been successfully targeted with poly (ADP-ribose) polymerase (PARP) inhibitors, leading to significant improvements in response rates and overall survival in patients with BRCA-mutated ovarian cancers." (PMID 37239452, 2023). "Treatment with poly(ADP-ribose) polymerase inhibitors (PARPis) has been evaluated for nearly 10 years in recurrent ovarian cancer—first in patients with a BRCA1/2 mutation and later in patients without a BRCA1/2 mutation." (PMID 36765776, 2023). "The BRCA1/2 mutations account for a small percentage of ovarian cancer, but the others are called sporadic, with no known genetic cause." (PMID 36981032, 2023). "Mutations in BRCA1 and BRCA2 genes have been known for decades to predispose to familial breast and ovarian cancers, and, more recently, prostate and pancreatic cancers have been added to the constellation of cancers that show increased prevalence in these families." (PMID 36975505, 2023). "Notably, similar to the BRCA1-methylation-positive patients with breast and ovarian cancers, miR-155-5p was significantly higher in the BRCA1-methylated carriers compared to age-matched controls (p = 0.0418)." (PMID 37240365, 2023). "Since the reversion of BRCA germline mutations has been reported to be associated with the acquisition of resistance to chemotherapy in ovarian cancer, we also searched for changes in BRCA1/2 mutations and we did not detect any germline mutation reversion." (PMID 38254917, 2023). "In this matched analysis of 430 women at a high risk of having ovarian cancer due to an inherited BRCA1 or BRCA2 mutation, we evaluated whether physical activity during adolescence and early-adulthood was associated with ovarian cancer." (PMID 38019076, 2023). "BRCA1/2 mutations account for less than 30% of ovarian cancer patients, and those who did not met the criteria for secondary platinum-sensitive relapse were excluded, as were those on maintenance therapy with PARPi or bevacizumab." (PMID 37891662, 2023). "Therefore, the detection of BRCA1 biomarker allows for the characterization of the genetic features and the screening of breast or ovarian cancer patients." (PMID 37112468, 2023). "This weak evidence reflects the high percentage of HGSC in ovarian cancer, irrespective of the presence of germline BRCA1 and BRCA2 pathogenic variants." (PMID 37076566, 2023). "Contrasting to the models of BRCA2-d, BRCA1-d in ovarian cancer was exclusively associated with clustered and non-clustered tandem duplications (1–10 kb)." (PMID 36883553, 2023). "Oral hormonal contraception should not be negated in BRCA1/BRCA2 mutation carriers not yet eligible for risk-reducing surgery because it significantly reduces the risk of developing ovarian cancer." (PMID 36835955, 2023). "BRCA1 and 2 are the best-characterised HRR genes and predispose to breast and ovarian cancer." (PMID 37365284, 2023). "Recent studies showed that results of the treatment with PARP1 inhibitors in breast and ovarian cancers may be dependent on high expression, particularly for miRNAs, and low expression of BRCA1." (PMID 36831687, 2023). "Patients diagnosed with epithelial ovarian cancer may undergo reflex tumour BRCA1/2 testing followed by germline BRCA1/2 testing in patients with a positive tumour test result." (PMID 38201604, 2023). "Especially, BRCA1/BRCA2 mutation carriers have an increased risk for breast and ovarian cancer." (PMID 37781206, 2023).
ovarian carcinoma (continued). "Forty-nine patients from families with a high risk of developing breast or ovarian cancer (Manchester score of > 34) without a known germline pathogenic BRCA1 mutation were examined." (PMID 36112334, 2023). "Although guidelines recommend prophylactic adnexectomy for BRCA1/2 mutation carriers within certain age ranges, there are instances where tumors arise at an earlier age or where patients never develop ovarian cancer at all." (PMID 37519818, 2023). "The GIS distribution for BRCA1/2-deficient TNBC tumors in this study was not statistically significantly different from ovarian cancer but was significantly different from ER + BC tumors." (PMID 37589839, 2023). "As major gatekeepers for genome integrity, both BRCA1 and BRCA2 encode proteins involved in DNA double-strand break (DSB) repair mechanisms and are, therefore, susceptibility genes for breast and ovarian cancer (OC)." (PMID 36614323, 2023). "We analyzed a cohort of 50 subjects with a previous personal history of breast or ovarian cancer who had not been tested for BRCA1/2 mutations at the time of diagnosis but were found eligible according to the most recent guidelines." (PMID 37723374, 2023). "The TOPACIO/KEYNOTE-162 Phase I/II study evaluated the combination of niraparib and pembrolizumab in patients with recurrent platinum-resistant ovarian cancer irrespective of BRCA1/2-mutation status." (PMID 37430137, 2023). "Additionally, heterozygous methylation of BRCA1 in BRCA1 methylated ovarian cancer PDX models is associated with PARP-is resistance, whereas complete BRCA1 methylation predicts clinical response to PARP-is." (PMID 37569269, 2023). "BRCA1 loss is not observed in sporadic BC and ovarian cancer (OC), of which the role of BRCA1 in BC appears to be limited to familial cases." (PMID 38275383, 2023). "To limit costs of genetic testing, we have proposed a testing strategy that involves paired germline and tumour BRCA1/2 testing in all patients diagnosed with epithelial ovarian cancer aged < 79 years old, while reserving tumour-first testing for those aged ≥ 80 years old." (PMID 38201604, 2023). "The risks of breast and ovarian cancers in female relatives of BRCA1 and BRCA2 carriers were significantly higher than female relatives of non-carriers (BRCA1: RR = 4.29, P < 0.001 and RR = 21.95, P < 0.001; BRCA2: RR = 4.19, P < 0.001 and RR = 4.65, P < 0.001, respectively)." (PMID 36861435, 2023). "Some studies have found a high frequency of VUS in HRR genes in ovarian cancer patients, but they have also shown that two decades of testing and research on BRCA1 and BRCA2 have led to a significant decrease in VUS rates in BRCA, which are lower than in most other genes." (PMID 36836518, 2023). "BRCA1 c.5266dup is the most frequent germline PV in Russian ovarian cancer patients." (PMID 37445679, 2023). "Genetic testing for pathogenic variants in BRCA1 and BRCA2 is widely available in breast and ovarian cancer, to enable not only early detection and risk reduction, but also to guide cancer treatment, e.g. consideration of the use of olaparib in chemotherapy regimens." (PMID 36927983, 2023). "This is of particular importance in BRCA1/2-driven breast and ovarian cancer cells." (PMID 37108225, 2023). "In Germany, women with newly identified BRCA1 or BRCA2 variants receive individual care and counseling on their genetic findings, cancer risks, and preventive options at the centers of the German Consortium of Familial Breast and Ovarian Cancer (GC-HBOC)." (PMID 37845719, 2023). "Screening for a diverse panel of BRCA1 and BRCA2 variants may be necessary to protect women in Arab populations who have a known family history of breast and/or ovarian cancer." (PMID 37306523, 2023). "Notably, BARD1 shares a structurally homologous domain with BRCA1, and these two proteins interact to impede the progression of different cancers, including breast and ovarian cancers, through the BRCA1-dependent pathway." (PMID 37727789, 2023).
ovarian carcinoma (continued). "Within the ovarian cancer subset, camonsertib anti-tumor activity was observed in patients with BRCA1-altered tumors previously treated with PARPi or platinum therapy, most notably in a post-PARPi-treated patient with a germline BRCA1 alteration, despite the presence of reversion mutations." (PMID 37277454, 2023). "However, many of the currently available treatment options, such as PARP inhibitors veliparib and olaparib, are targeted agents for patients with BRCA1 and/or BRCA2 mutations and are therefore ineffective for many ovarian cancer patients." (PMID 36671544, 2023). "The combination of pan-EGFR inhibitor neratinib was synergistic with niraparib in ovarian cancer cell lines as well, leading to the ongoing clinical trial evaluating the combination in patients with platinum-resistant, BRCA1/2 wild-type ovarian cancer (NCT04502602)." (PMID 37430137, 2023). "Data for 10,373 ovarian cancer cases, including carriers and non-carriers of BRCA1 or BRCA2 pathogenic variants, were collected from unpublished international cohorts and consortia and published studies." (PMID 37076566, 2023). "The BRCA1 (OMIM # 113705) and BRCA2 (OMIM# 612555) genes are the most common and exhaustively studied, with a lifetime risk of developing cancer for BRCA mutation carriers of 60–80% for breast and 20–40% for ovarian cancers." (PMID 37444530, 2023). "Since our analysis goes back to 2003, when BRCA1/2 genetic testing was not a routine test for ovarian cancer patients in Greece, data regarding BRCA1/2 mutation status are limited and therefore not included in the multivariate analysis." (PMID 37444629, 2023). "In the Paola/ENGOT-ov25 phase III trial, the 5-year overall survival (OS) rates in patients with BRCA1/2 mutations and/or with HRD-positive newly diagnosed advanced ovarian cancer were 65% and 55%, respectively, with olaparib and bevacizumab as a maintenance treatment." (PMID 38067228, 2023). "Thus, we sought to evaluate the expression levels and clinical significance of miR-155-5p in peripheral WBCs in patients with ovarian cancer, including BRCA1-methylation-positive patients." (PMID 37240365, 2023). "BRCA deficiency was originally shown to result from coding mutations affecting the BRCA1 or BRCA2 genes, which are the principal determinants of genetic predisposition to breast and ovarian cancers and play central role in Homologous Recombination (HR) Repair, also called BRCA pathway." (PMID 37007122, 2023). "However, women with pathogenic BRCA1 or BRCA2 mutations have a 55-72% and 45-69% chance of developing ovarian cancer by age 80, respectively." (PMID 37228496, 2023). "In addition to BRCA1 and BRCA2 genes belonging to the Fanconi anemia pathway, mutations in PALB2, ATM, RAD51C/D and BRIP1 are also known to increase the risk of ovarian cancer." (PMID 37746296, 2023). "Women with inherited mutations in the BRCA1 or BRCA2 genes have increased lifetime risks for developing breast and/or ovarian cancer and may develop these cancers around the age of 30 years." (PMID 37365514, 2023). "Notably, transheterozygotes who have inherited deleterious mutations in both BRCA1 and BRCA2 were first reported in a Hungarian patient with breast/ovarian cancer." (PMID 37686625, 2023). "BRCA-1/2 mutation carriers develop breast and ovarian cancer on average 20 years earlier than non-mutation carriers." (PMID 37365514, 2023). "Identifying additional biomarkers to expand this treatment in somatic BRCA1/2-mutant or HR-related-gene-mutant advanced breast or ovarian cancers could significantly benefit patients who would otherwise receive chemotherapies as the only regimen." (PMID 38098088, 2023). "Inability to screen high-risk populations: Existing screening methods often do not identify ovarian cancer in high-risk populations, such as women with a family history of ovarian cancer or known genetic mutations like BRCA1 and BRCA2." (PMID 38084173, 2023).
ovarian carcinoma (continued). "Notably, the majority of these mutations (56, representing 39.4%) was identified in the BRCA1/BRCA2 genes, primarily associated with breast (26.7%) and ovarian cancer (8.4%) syndromes." (PMID 38201513, 2023). "This upregulation occurs in both BRCA1/2-mutated and -WT cells, but only affects PARPi sensitivity in BRCA1/2-mutated cells, further supporting our previous findings that ALDH1A1 inhibitor can only be used to treat HR-deficient ovarian cancer cells in combination with PARPi12." (PMID 37429899, 2023). "Certain germline mutations in BRCA1 and BRCA2 are known to increase the risk of ovarian cancer." (PMID 36981032, 2023). "Breast cancer susceptibility gene 1 (BRCA1) is a key member of the ATM-mediated DDR and directs the homologous recombination repair (HR) pathway, and mutations in this gene are associated with ovarian cancers." (PMID 38137018, 2023). "Somatic mutations in BRCA1 or BRCA2 genes are also occasionally present in sporadic (non-hereditary) ovarian cancers." (PMID 35203410, 2022). "The BRCA1 and BRCA2 genes are associated with hereditary breast and ovarian cancer." (PMID 35785170, 2022). "Apart from the serous epithelial ovarian cancer, patients with a family history of ovarian cancer were more likely to carry BRCA1/2 mutations regardless of their family histories." (PMID 35608067, 2022). "Genetic counseling and testing for germline variants in BRCA1 and BRCA2 and in other hereditary breast and/or ovarian cancer (HBOC) susceptibility genes was established when the significance of hereditary cancer screening and preventive measures was recognized." (PMID 35326583, 2022). "However, the majority of ovarian cancer patients harbor wild-type (WT) BRCA1/2 status, which narrows its clinical application." (PMID 36267463, 2022). "Therefore, downregulating PKM2 protein level resulted in defective HR pathway in BRCA1 wild type ovarian cancer cells." (PMID 35280680, 2022). "Among the 10 recurrently found gBRCA1/2-PV (in more than 10 families) in the Japanese Organization Of Hereditary Breast and Ovarian Cancer (JOHBOC) registry in Japan, only three variants, BRCA1:c.2800C>T, BRCA2:c.6952C>T, and BRCA2:c.9076C>T, were identified in our OC cases." (PMID 35741847, 2022). "In addition, genes that involved in regulating this pathway, such as ADRB1, a β-adrenocepter that can promote the production of cAMP, were up-regulated in BRCA1-defective ovarian cancer patients." (PMID 35517499, 2022). "We investigated whether the inhibition of the polyamine biosynthetic pathway with DFMO can increase rucaparib sensitivity of four wildtype BRCA1/2 ovarian cancer cell lines." (PMID 35736348, 2022). "Similarly, stage III or IV ovarian cancer patients with tumors that were BRCA1/2m had significantly better OS than patients with BRCA1/2 wt tumors of the same stage (HR = 0.64 (95% CI = 0.55–0.75))." (PMID 35909902, 2022). "Although originally identified in a mouse model of BRCA1-mutant cancer, ABCB1 gene fusions that enhance activity have been observed in treatment-refractory breast and ovarian cancers, implying this could also be a cause of clinical PARPi resistance." (PMID 35892198, 2022). "Moreover, multiple reversion events in BRCA1/2 genes have been reported as a mechanism of platinum-resistance in a study of whole-genome characterization of chemo-resistant ovarian cancer." (PMID 35326571, 2022).
ovarian carcinoma (continued). "Similar analyses were performed only in BRCA1/2 wild-type ovarian cancer cell lines." (PMID 36291176, 2022). "Binomial logistic regression was applied to assess the association of standardized PRSs with either ED or LD under adjustment for patient recruitment criteria for germline testing and localization of BRCA1/2 PVs in the corresponding BC or ovarian cancer (OC) cluster regions." (PMID 35761208, 2022). "Besides BRCA1/2, the implication in CRC occurrence of FANCJ/BRIP1 mutations, a moderate-risk factor for ovarian cancer, has attracted considerable attention." (PMID 35330396, 2022). "In addition to ovarian cancers, Olaparib has been approved to treat pancreatic ductal adenocarcinoma (PDAC) patients with germline BRCA1/2 mutations." (PMID 36324587, 2022). "A better understanding of breast and ovarian cancer’s clinical features along with screening of BRCA1 and BRCA2 in the community may lead to timely diagnosis and management." (PMID 36197199, 2022). "Germline BRCA1/2-associated epithelial ovarian cancer has been associated with better progression-free survival and overall survival than sporadic epithelial ovarian cancer, but conclusive data are lacking." (PMID 36137114, 2022). "The American Society of Clinical Oncology recommends that all women with epithelial ovarian cancer should obtain genetic testing for inherited variants in BRCA1/2 and similar susceptible genes without regard to their family history." (PMID 36013212, 2022). "Based on this premise, our studies demonstrated the first evidence that a combination of the PARP inhibitors and a small compound named SN-38, which individually have poor therapeutic effects, exhibited a greatly synergistic impact on BRCA1/2-proficient ovarian cancer." (PMID 36267463, 2022). "Mutations in BRCA (BRCA1 and BRCA2) genes are also one of the major causes of ovarian cancers." (PMID 36415372, 2022). "The NCCN recommends risk-reducing salpingo-oophorectomy (RRSO), typically between 35 and 40 years, and upon completion of childbearing in BRCA1 mutation, while it is reasonable to delay RRSO for management of ovarian cancer risk until age 40-45 years in patients with BRCA2." (PMID 35888662, 2022). "In this study, ovarian cancer cell lines we used has wild-type BRCA1." (PMID 36703740, 2022). "The analysis should be able to detect damaging variants in all genes associated to ovarian cancer susceptibility, rather than just BRCA1/2 genes." (PMID 36010882, 2022). "Moreover, cediranib was found in breast and ovarian cancer xenografts to suppress the expression of BRCA1/2 and RAD51, inducing HRD state." (PMID 36358724, 2022). "In addition to increased familial BC and ovarian cancer risk due to BRCA1 and BRCA2 germline mutations, approximately 40–45% of all hereditary BCs harbor BRCA1 germline mutations and 35–40% harbor BRCA2 germline mutations." (PMID 36140723, 2022). "Consensus guidelines for hereditary breast and ovarian cancer include management recommendations for pathogenic/likely pathogenic (P/LP) variants in ATM, CHEK2, PALB2, and other DNA damage repair (DDR) genes beyond BRCA1 or BRCA2." (PMID 35626031, 2022). "Our findings suggest that while biallelic loss of BRCA1/2 may be sufficient to detect the majority of cases of the HRD-phenotype in breast and ovarian cancer, more work is needed to identify the relationship between genotype and HRD in other cohorts." (PMID 35643464, 2022). "In ovarian cancer, BRCA1 has 9.8% prevalence, followed by BRCA2 at 4.9%." (PMID 34979999, 2022). "Such tumor initiation process is linked to EMT in BRCA1+ breast cancer, but this has not yet been investigated in ovarian cancer." (PMID 36076202, 2022). "Few studies have examined the characteristics of somatic mutations in HRR pathway genes other than BRCA1/2, and the impact of these mutations on treatment efficacy and prognosis in patients with ovarian cancer is not clear." (PMID 38089758, 2022).